RPS26P31 (ribosomal protein S26 pseudogene 31)
Synonyms: RPS26_8_840
Gene: Processed pseudogene on chromosome 7 (122,681,315 to 122,681,662, forward strand). Ensembl gene ENSG00000235459.
Diseases named in the same sentence as RPS26P31 in open-access papers:
RPS26P31 is named in the same sentence as 2 diseases in open-access papers, as found by Europe PMC text mining. Sharing a sentence is not in itself a finding about the gene and the disease. The quoted sentences say what the papers report.
ovarian carcinoma (1 paper, 2019). A malignant neoplasm originating from the surface ovarian epithelium. "All these findings indicated that RPS26P15, AC004057.1, RPS26P31, RPS26P6, RPS26P3 and RPS26P47 were the most potential pseudogenes in regulating hsa-miR-363-3p in ovarian cancer." (PMID 31794425, 2019). "Among 56 predicted pseudogenes, only 6 pseudogenes (RPS26P15, AC004057.1, RPS26P31, RPS26P6, RPS26P3 and RPS26P47) were significantly upregulated in cancer samples (compared to normal samples) and advanced stage of ovarian cancer (compared to early stage ovarian cancer)." (PMID 31794425, 2019).
cancer (1 paper, 2019). A tumor composed of atypical neoplastic, often pleomorphic cells that invade other tissues. "Finally, only 6 pseudogenes, RPS26P15, AC004057.1, RPS26P31, RPS26P6, RPS26P3 and RPS26P47 were significantly upregulated in cancer tissues when compared with normal controls." (PMID 31794425, 2019).